ACP1 (acid phosphatase 1)
Description:
Acts on tyrosine phosphorylated proteins, low-MW aryl phosphates and natural and synthetic acyl phosphates with differences in substrate specificity between isoform 1 and isoform 2. [Isoform 3]: Does not possess phosphatase activity.
Synonyms: LMW-PTP; HAAP; LMWPTP
Tractability: Small molecule: a structure with a bound ligand is known; a high-quality ligand is known; it belongs to a druggable protein family. Antibody: its Gene Ontology location is reachable by antibodies, with medium confidence. PROTAC: ubiquitination databases record sites on it; its protein half-life has been measured; a small molecule that binds it is known.
Target class: Tyrosine protein phosphatase; Enzyme; Phosphatase; Protein Phosphatase
Chemical probes: ML400
Gene: Protein-coding gene on chromosome 2 (264,140 to 279,100, forward strand). Ensembl gene ENSG00000143727.
Subcellular location: Cytoplasm
Subcellular location (Human Protein Atlas): Nucleoplasm; Cytosol
Gene Ontology:
Molecular function: acid phosphatase activity; protein binding; protein tyrosine phosphatase activity; non-membrane spanning protein tyrosine phosphatase activity; SH3 domain binding
Biological process: chemical synaptic transmission
Cellular component: cytoplasm; cytoplasmic side of plasma membrane; extracellular exosome; synapse
Genetic constraint (gnomAD): Loss-of-function variants: 19 observed, 17.98 expected, observed/expected ratio (o/e) 1.06, 90% interval 0.74 to 1.55. The upper end of that interval is the gene's LOEUF score, 1.55, which puts it in group 6 of 6, group 1 being the genes least tolerant of losing a copy. Missense variants: 157 observed, 166.28 expected, observed/expected ratio (o/e) 0.94, 90% interval 0.83 to 1.08. Synonymous variants: 63 observed, 59.03 expected, observed/expected ratio (o/e) 1.07, 90% interval 0.87 to 1.32.
Homologues: Orthologues: macaque ACP1 (98% identical), chimpanzee ACP1 (93% identical), mouse Acp1 (85% identical), rat Acp1 (81% identical), pig ACP1 (77% identical), Drosophila melanogaster Argp (42% identical), Drosophila melanogaster CG14297 (28% identical). Paralogues in human: PTRHD1 (16% identical).
Diseases named in the same sentence as ACP1 in open-access papers:
ACP1 is named in the same sentence as 51 diseases in open-access papers, as found by Europe PMC text mining. Sharing a sentence is not in itself a finding about the gene and the disease. The quoted sentences say what the papers report.
Obesity (5 papers, 2013 to 2025). Accumulation of substantial excess body fat. "The increased risk of T2DM associated with ACP1 seems to be mediated through increased risk of obesity in humans, although one study found an association with a polymorphism in this gene with insulin resistance in males, irrespective of BMI." (PMID 34874954, 2021). "We observed a nominally significant association for only two T2D markers in RREB1 and PRKAG1, one obesity (OB) marker in the OR2Y1 gene, and for several BMI markers in the ACP1, RBBP6, and C14orf39 genes." (PMID 30126146, 2018). "A SNP in ELOVL3 showed potential association with both type 2 diabetes, fasting plasma glucose and waist circumference while two SNPs in ACP1 and SLC27A4 were selected from analyses of obesity, BMI and waist circumference." (PMID 23160641, 2013).
breast carcinoma (4 papers, 2013 to 2020). "For example, tyrosine-protein kinase receptor (EPHA2) is a prominent substrate of ACP1 and its kinase activity regulated by ACP1 can induce the cell transformation in breast cancer." (PMID 32787954, 2020). "Remarkably, three enhanced looping genes in resistant breast cancer cells, ACP1, HECTD1, and MBIP, identified and validated by HiSIF and 3C/RT-qPCR, have been previously shown to be involved in breast cancer cell transformation and progression." (PMID 32787954, 2020).
colorectal cancer (4 papers, 2015 to 2025). A primary or metastatic malignant neoplasm that affects the colon or rectum. "To understand the role of LMWPTP in colorectal cancer, we first investigated the gene expression levels of ACP1 using publicly available microarray datasets from Affymetrix Platforms." (PMID 25811796, 2015).
diabetes (3 papers, 2014 to 2021). "Several SNPs have been identified which provide moderate to strong evidence of association to DM in the cat being located within a haplotype block spanning genes that have been associated with human diabetes (ACP1 and TMEM18)." (PMID 34874954, 2021). "Mutations in our prime candidate ACP1 (ENST00000272065) have been associated with diabetes." (PMID 34469537, 2021). "The ACP1 genetic polymorphism is associated with a CAD risk in females with diabetes." (PMID 25123136, 2014).
type 2 diabetes (3 papers, 2013 to 2023). "SNP rs3828329 on 2p25.3 in the ACP1 gene is has been shown to be significantly associated with fasting insulin and insulin sensitivity in type 2 diabetes in Mexican-Americans." (PMID 25123136, 2014).
COVID-19 (2 papers, 2020 to 2022). A disease caused by infection with severe acute respiratory syndrome coronavirus 2. "There was a highly overlapped rate of these up-DEGs between moderate and severe COVID-19 groups, including ACP1, S100A8, and A100A9 (18/20 = 90%)." (PMID 35172892, 2022).
dyslipidemia (2 papers, 2014 to 2019). "From a genetic perspective, genome-wide association studies (GWAS) identified a region on 2p25 that influences risk for attempting suicide and contains the ACP1 gene and polymorphisms in ACP1 which were found to modulate both protection and predisposition to dyslipidemia." (PMID 30881317, 2019).
schizophrenia (2 papers, 2019 to 2023). A major psychotic disorder characterized by abnormalities in the perception or expression of reality. "Only one group reported the association of p190RhoGAP with the pathway of acid phosphatase 1 (ACP1), which was associated with suicide attempts in Caucasians with primary diagnoses of schizophrenia and schizoaffective disorder." (PMID 37958606, 2023). "With the aim to validate several genetic biomarkers associated with suicide attempts in patients with schizophrenia, Li and collaborators confirmed acid phosphatase 1 (ACP1) as a top predictor of suicide attempts." (PMID 31013840, 2019).
acute lymphoblastic leukaemia (1 paper, 2025). "Research has shown that certain polymorphisms in the ACP1 gene are associated with an increased risk of bone necrosis in children undergoing treatment for acute lymphoblastic leukaemia, indicating a potential role for ACP1 in the pathogenesis of bone necrosis." (PMID 41498029, 2025).
adenoma (1 paper, 2015). A neoplasm arising from the epithelium. "While the cause of the specific upregulation of ACP1 mRNA has yet to be identified, interestingly, an initial database analysis (MENT methylation and expression database) suggests that this gene is hypomethylated in adenoma and cancer samples." (PMID 25811796, 2015). "Therefore, we also examined ACP1 expression levels in adenoma samples and again observed an increased mRNA expression in these samples (n = 32) compared to their normal adjacent colon tissue (P < 0.0001)." (PMID 25811796, 2015).
Autoimmunity (1 paper, 2011). The occurrence of an immune reaction against the organism's own cells or tissues. "Since the association of ACP1 gene with autoimmunity has previously been described, in the present study we sought to investigate the possible association of ACP1 polymorphisms with RA." (PMID 21767392, 2011).
Coronary artery disease (1 paper, 2013). "We have recently reported an association between a phosphoprotein phosphatase controlled by Acid Phosphatase locus 1 (ACP1), and Coronary artery disease (CAD) suggesting an effect on the susceptibility to this disease." (PMID 28352429, 2013). "We have recently reported an association between Coronary Artery Disease (CAD) and Acid Phosphatase locus 1 (ACP1) suggesting a role of ACP1 in the susceptibility to CAD." (PMID 28352429, 2013).
hypertrophic cardiomyopathy (1 paper, 2011). A condition in which the myocardium is hypertrophied without an obvious cause. "Moreover, patients with hypertrophic cardiomyopathy, an autosomal dominant disease, were found to have the highest frequencies for ACP1*C allele and showed a linear relationship between maximum wall thickness and the amount of total LMW-PTP activity." (PMID 21767392, 2011).
infarction (1 paper, 2013). A localised pathological necrosis of tissue resulting from obstruction of the blood supply usually by a thrombus, an embolus, or vascular torsion. "The association of cNYHA class and low LVEF with ACP1 genotypes is more marked in subjects with previous history of infarction." (PMID 28352429, 2013). "We have considered the effect of sex, history of previous infarction and age on the relationship of low LVEF and cNYHA class with ACP1 genotypes in CAD diabetics." (PMID 28352429, 2013).
myopia (1 paper, 2024). "ACP1 is significantly upregulated in retinal protein expression in myopic guinea pigs, and a joint meta-analysis has identified ACP1 as a novel locus associated with myopia in European pedigrees." (PMID 39408566, 2024).
osteonecrosis (1 paper, 2019). A none disease characterized by death of bone tissue due to a lack of blood supply. "In another GWAS study, SNPs in the ACP1 gene (acid phosphatase 1) were associated with an increased risk of osteonecrosis during dexamethasone treatment of pediatric ALL." (PMID 30832275, 2019). "The gene, ACP1, is important for regulating cholesterol and triglyceride levels, meaning that lipid levels are possibly relevant in the pathology of osteonecrosis in pediatric ALL." (PMID 30832275, 2019).
rheumatoid arthritis (1 paper, 2011). A chronic, systemic autoimmune disorder characterized by inflammation in the synovial membranes and articular surfaces. "The aim of this study was to determine the contribution of ACP1 polymorphisms to susceptibility to rheumatoid arthritis (RA), as well as the potential contribution of these polymorphisms to the increased risk of cardiovascular disease (CV) observed in RA patients." (PMID 21767392, 2011).
cancer (13 papers, 2012 to 2023). A tumor composed of atypical neoplastic, often pleomorphic cells that invade other tissues. "Although lacking prior associations with HPV infection or cervical lesions, the ACP1 genetic variation has been linked to other cancer types." (PMID 37891885, 2023). "Common variants of ACP1 were shown to be associated with the risk of multiple diseases, such as favism, cancer, type 1 diabetes (T1D) and cardiovascular events." (PMID 25123136, 2014). "Expression of the LMWPTP encoding gene ACP1 (transcript 215227) was compared between CRC and normal adjacent colonic tissue (n = 17), and found to be significantly increased in the carcinoma group (P = 0.0005)." (PMID 25811796, 2015). "Acid phosphatase locus 1 (ACP1) is a member of the phosphotyrosine protein phosphatase family of proteins and is involved in metabolic signaling, growth signaling, immunological diseases and cancer development." (PMID 25123136, 2014). "Among these 10 hubs are 5 – ACP1, HSP90AA1, LEF1, MLH1, and RBM5 - common to the major identified cancer-related pathways." (PMID 27809917, 2016). "In addition to 4 same genes (KIAA0090, ATAD3B, TRIM27 and DMTF1) with LUSC-C1, ACP1 and SH3YL1 also played important roles in cancer." (PMID 33549049, 2021).
tumor (11 papers, 2012 to 2025). "The tumor of ACP1 shows only few vital tumor cells but regressive changes with wet keratin and calcifications predominate." (PMID 29795641, 2018). "This accords with significantly increased ADC values in ACP2 derived xenografts relative to ACP1 and ACP3 PDX, and higher average vital tumor content." (PMID 29795641, 2018). "In concordance with the histologically assessed tumor vitality, varying on average between <10% (ACP1, n = 7), ~41% (ACP2, n = 10) and ~26% (ACP3, n = 10), the T2 volume of ACP2 differs significantly from ACP1 and ACP3." (PMID 29795641, 2018).
infection (5 papers, 2015 to 2022). The state of being infected such as from the introduction of a foreign agent such as serum, vaccine, antigenic substance or organism. "vulgaris interaction the expression of the gene (acp1), encoding an acid protease, and the gene aspS, encoding an aspartyl protease, was low at the beginning of infection but increased at the stage of spreading necrosis." (PMID 26579080, 2015). "The gene acp1, which encodes an acid protease, was highly expressed from the beginning of infection, and presented the highest level of expression at 72 hpi." (PMID 26579080, 2015). "By contrast, when tested in a mouse infection model, a 1000-fold increase in bacterial load was detected for both acp1 and acp3 deletion mutants, indicating that both Acp1 and Acp3 play a role in P. aeruginosa pathogenicity in vivo." (PMID 30294316, 2018). "Previous studies have showed that acp1 and acp3 expression is regulated by quorum sensing (QS) and acp3 is highly induced during infection." (PMID 30294316, 2018). "Arabidopsis Acyl Carrier Protein 1 (ACP1), a small essential protein functioned as a carrier of the acyl intermediates in the fatty acid synthesis pathway, has a low expression in leaves, but can be induced and play an important role in plant immunity to bacterial pathogen infection." (PMID 36361594, 2022). "During early infection, a previously characterized non-aspartyl acid protease (acp1; Sscle11g082980) was found to be the most upregulated (logFC = 6.22 at 24 hpi)." (PMID 30808300, 2019).
ACP1 also shares sentences with these, for which no sentence is quoted: cardiovascular disease (3 papers); melanoma (3); adenocarcinoma (1); Alzheimer disease (1); bipolar disorder (1); bladder cancer (1); breast tumor (1); cardiac hypertrophy (1); chronic lymphocytic leukemia (1); chronic myeloid leukemia (1); colon cancer (1); colorectal adenoma (1); depression (1); epilepsy (1); Friedreich ataxia (1); gangrene (1); glaucoma (1); heart failure (1); Hypercholesterolemia (1); hypertriglyceridemia (1); Insulin resistance (1); leukemia (1); lung adenocarcinoma (1); metastatic melanoma (1); osteoporosis (1); ovarian carcinoma (1); prostate carcinoma (1); schizoaffective disorder (1); senile cataract (1); serous ovarian cancer (1).
A further 1 disease shares a sentence with ACP1 in 1 paper.